ZNF586 (zinc finger protein 586)
Description:
May be involved in transcriptional regulation.
Synonyms: FLJ20070
Tractability: PROTAC: ubiquitination databases record sites on it.
Gene: Protein-coding gene on chromosome 19 (57,769,655 to 57,819,939, forward strand). Ensembl gene ENSG00000083828.
Subcellular location: Nucleus
Subcellular location (Human Protein Atlas): Nucleoli fibrillar center; Vesicles
Pathways (Reactome):
Gene expression (Transcription): Generic Transcription Pathway
Gene Ontology:
Molecular function: DNA-binding transcription factor activity, RNA polymerase II-specific; RNA polymerase II cis-regulatory region sequence-specific DNA binding
Biological process: regulation of transcription by RNA polymerase II; regulation of DNA-templated transcription
Cellular component: nucleus
Genetic constraint (gnomAD): Loss-of-function variants: 8 observed, 7.21 expected, observed/expected ratio (o/e) 1.11, 90% interval 0.64 to 1.81. That is too few expected variants to judge how well the gene tolerates losing a copy. Missense variants: 442 observed, 506.68 expected, observed/expected ratio (o/e) 0.87, 90% interval 0.81 to 0.94. Synonymous variants: 166 observed, 175.21 expected, observed/expected ratio (o/e) 0.95, 90% interval 0.83 to 1.08.
Homologues: Orthologues: chimpanzee ZNF586 (99% identical), tropical clawed frog zfx (24% identical), mouse Zfy1 (23% identical), rat Zfy1 (23% identical), zebrafish zfx (23% identical), mouse Zfy2 (23% identical). Paralogues in human: ZNF551 (58% identical), ZNF418 (57% identical), ZNF256 (56% identical), ZNF304 (54% identical), ZNF587B (54% identical), ZNF792 (53% identical), ZNF548 (51% identical), ZNF549 (49% identical), ZNF583 (46% identical), ZNF570 (45% identical), ZNF79 (45% identical), ZNF419 (45% identical), and 26 more.
Diseases named in the same sentence as ZNF586 in open-access papers:
ZNF586 is named in the same sentence as 2 diseases in open-access papers, as found by Europe PMC text mining. Sharing a sentence is not in itself a finding about the gene and the disease. The quoted sentences say what the papers report.
esophageal cancer (1 paper, 2023). A primary or metastatic malignant neoplasm involving the esophagus. "Results indicate that ZNF91, and ZNF586 were upregulated in esophageal cancer tissue than adjacent tissue, whereas ZNF502, ZNF865, ZNF106, and ZNF225 was downregulated." (PMID 37013470, 2023).
ZNF586 also shares sentences with these, for which no sentence is quoted: tumor (1 paper).